DHX57 (DExH-box helicase 57)
Description:
Probable ATP-binding RNA helicase.
Synonyms: DDX57
Tractability: PROTAC: ubiquitination databases record sites on it; its protein half-life has been measured.
Gene: Protein-coding gene on chromosome 2 (38,797,724 to 38,875,938, reverse strand). Ensembl gene ENSG00000163214.
Subcellular location (Human Protein Atlas): Cytosol
Gene Ontology:
Molecular function: protein binding; RNA binding; helicase activity; ATP binding; ATP hydrolysis activity; metal ion binding; nucleic acid binding; RNA helicase activity; RNA polymerase binding
Biological process: positive regulation of translation
Genetic constraint (gnomAD): Loss-of-function variants: 88 observed, 141.52 expected, observed/expected ratio (o/e) 0.62, 90% interval 0.52 to 0.74. The upper end of that interval is the gene's LOEUF score, 0.74, which puts it in group 3 of 6, group 1 being the genes least tolerant of losing a copy. Missense variants: 1,646 observed, 1,546.2 expected, observed/expected ratio (o/e) 1.06, 90% interval 1.02 to 1.11. Synonymous variants: 621 observed, 558.03 expected, observed/expected ratio (o/e) 1.11, 90% interval 1.04 to 1.19.
Homologues: Orthologues: chimpanzee DHX57 (99% identical), macaque DHX57 (98% identical), dog DHX57 (92% identical), pig DHX57 (92% identical), guinea pig DHX57 (90% identical), rabbit DHX57 (88% identical), mouse Dhx57 (87% identical), rat Dhx57 (87% identical), tropical clawed frog dhx57 (69% identical), zebrafish dhx57 (60% identical), Drosophila melanogaster CG1582 (37% identical). Paralogues in human: DHX36 (30% identical), DHX29 (29% identical), DHX9 (26% identical), YTHDC2 (26% identical), DHX30 (23% identical), DHX34 (20% identical), DHX16 (19% identical), DHX8 (19% identical), TDRD9 (18% identical), DHX37 (18% identical), DHX38 (18% identical), DHX15 (17% identical), and 6 more.
Diseases named in the same sentence as DHX57 in open-access papers:
DHX57 is named in the same sentence as 2 diseases in open-access papers, as found by Europe PMC text mining. Sharing a sentence is not in itself a finding about the gene and the disease. The quoted sentences say what the papers report.
spermatogenic failure (1 paper, 2023). A male infertility characterized by dirsuption of the process of sperm development from diploid cells into mature haploid spermatozoa. "Our study found that the expression of SI (sucrase-isomaltase) and DHX57 (DExH-box helicase 57) was reported in healthy testis, but the expression of both genes decreased significantly in NOA patients, which might indicate abnormalities in glycometabolism and RNA metabolism in spermatogenic failure." (PMID 36945018, 2023).
tumor (2 papers, 2012 to 2014). "Thus we hypothesise that the DHX57:TMEM178:MAP4K3 is activating as disruption of the protein would otherwise seem incompatible with tumour cell growth and proliferation." (PMID 24548782, 2014). "In addition, CFTR was a chloride channel and the cause of cystic fibrosis; DHX57 was a putative ATP-dependent RNA helicase truncated in this TCC tumor; and ASTN1 was a neuronal adhesion molecule shown to be mutant in previous tumor studies." (PMID 23587365, 2012).